PVALB (parvalbumin)
Description:
In muscle, parvalbumin is thought to be involved in relaxation after contraction (By similarity). It binds two calcium ions.
Synonyms: D22S749
Tractability: No criterion of Open Targets' tractability assessment is met for any kind of drug.
Gene: Protein-coding gene on chromosome 22 (36,800,682 to 36,819,479, reverse strand). Ensembl gene ENSG00000100362.
Subcellular location (Human Protein Atlas): Nucleoplasm; Cell Junctions; Nucleoli
Gene Ontology:
Molecular function: calcium ion binding
Biological process: relaxation of muscle; excitatory chemical synaptic transmission; gene expression; inhibitory chemical synaptic transmission
Cellular component: cytoplasm; axon; synapse
Genetic constraint (gnomAD): Loss-of-function variants: 9 observed, 9.93 expected, observed/expected ratio (o/e) 0.91, 90% interval 0.55 to 1.56. That is too few expected variants to judge how well the gene tolerates losing a copy. Missense variants: 131 observed, 139.89 expected, observed/expected ratio (o/e) 0.94, 90% interval 0.81 to 1.08. Synonymous variants: 57 observed, 52.83 expected, observed/expected ratio (o/e) 1.08, 90% interval 0.87 to 1.35.
Homologues: Orthologues: chimpanzee PVALB (99% identical), dog PVALB (94% identical), macaque PVALB (93% identical), pig PVALB (93% identical), mouse Pvalb (87% identical), guinea pig PVALB (80% identical), rat Pvalb (79% identical), zebrafish pvalb7 (66% identical), tropical clawed frog pvalb (65% identical), zebrafish pvalb6 (63% identical), rabbit PVALB (55% identical). Paralogues in human: OCM (51% identical), OCM2 (51% identical).
Diseases named in the same sentence as PVALB in open-access papers:
PVALB is named in the same sentence as 144 diseases in open-access papers, as found by Europe PMC text mining. Sharing a sentence is not in itself a finding about the gene and the disease. The quoted sentences say what the papers report.
schizophrenia (243 papers, 2009 to 2026). A major psychotic disorder characterized by abnormalities in the perception or expression of reality. "Reduced cortical inhibition by parvalbumin-expressing (PV) interneurons in schizophrenia is thought to be associated with impaired processing in the prefrontal cortex and altered EEG signals such as oddball mismatch negativity (MMN)." (PMID 42228689, 2026). "The schizophrenia susceptibility genes detected in inh-PVALB were associated with the KEGG Pathway ‘Phosphatidylinositol signalling pathway’ and GO terms ‘lipid modification’ and ‘glycerolipid metabolic process’." (PMID 39397771, 2025). "Parvalbumin interneurons (PV-INs), which are implicated in schizophrenia, play a role in inhibiting GABAergic synaptic networks, helping to maintain the balance of excitation-inhibition and signal coordination between brain regions." (PMID 40612741, 2025). "Sulforaphane pre-treatment protects from oxidative damage, reducing 8-oxo-dG positive cells to the level observed in control animals and preventing loss of parvalbumin-positive cells, thereby preventing schizophrenia-like behaviors." (PMID 40686501, 2025). "MIA during pregnancy has been associated with cognitive deficits and reduced parvalbumin immunoreactivity in the mPFC of adult offspring—alterations characteristic of schizophrenia." (PMID 40722922, 2025). "The prefrontal cortex is also heavily implicated in schizophrenia onset, where impairments in parvalbumin neurons have been linked to schizophrenia-like phenotypes in mice." (PMID 39125882, 2024). "Impairment of the ventral subiculum parvalbumin interneuron population underlies dopamine dysregulation in schizophrenia animal models." (PMID 37945756, 2023). "Genetic and epigenetic abnormalities in cortical parvalbumin-positive GABAergic interneurons and consequent alterations in glutamate-mediated excitatory neurotransmission during early neurodevelopment underlie schizophrenia manifestation and progression." (PMID 36946488, 2023). "Impairment of parvalbumin interneurons induced by oxidative stress (OxS) is a “hub” on which converge several genetic and environmental risk factors associated with schizophrenia." (PMID 35079122, 2022). "We propose describing some of the mechanisms linked to the maturation of inhibitory parvalbumin-expressing interneurons, and we will discuss the anomalies related to the functioning of these inhibitory cells that have been observed in schizophrenia patients." (PMID 36590919, 2022). "Similar to observations in patients with MCT8 mutations, loss of parvalbumin expression has been observed in the brains of patients with schizophrenia and autism." (PMID 34955723, 2021). "Other studies have demonstrated that aberrations in parvalbumin interneurons are implicated in schizophrenia and that elevated IL-6 levels in CNS disrupt working memory." (PMID 33746786, 2021). "Patients with schizophrenia often have impaired frontal cortex gamma band oscillations, which are associated with parvalbumin interneuron dysfunction and aberrant cognitive and perceptual functions." (PMID 33907230, 2021). "Transcriptional dysregulation of PGC-1α in parvalbumin interneurons causes altered inhibition, which represents a consistent pathophysiological feature of schizophrenia." (PMID 34746116, 2021). "Parvalbumin neurons are the largest population in cortical GABAergic neurons and are implicated in the pathogenesis of schizophrenia." (PMID 33325157, 2021). "Perineuronal nets (PNNs) associated with parvalbumin-positive interneurons (PVs) in the prefrontal cortex (PFC) are dysregulated in schizophrenia." (PMID 34681799, 2021). "Here we report that in the apomorphine-susceptible (APO-SUS) rat model, which has schizophrenia-like features, a myelination defect occurred specifically in parvalbumin interneurons." (PMID 32393757, 2020).
schizophrenia (continued). "Secondly, we propose that van Gogh suffered from a defective function of parvalbumin interneurons, which seems likely given his family history of schizophrenia and his addiction to substances associated with GABA action." (PMID 32754073, 2020). "Ontological enrichment analysis further revealed that the top 500 genes correlated with PVALB in the AHBA data contained genes associated to schizophrenia, neuronal signaling, and gated channel activity." (PMID 32514083, 2020). "VPP1 was altered in the non-schizophrenia suicide group and increased levels of parvalbumin were linked to antipsychotics." (PMID 32639965, 2020). "Comparing the RSFA-schizophrenia polygenic risk map to all genes, PVALB was the among the top 0.83% negatively correlated expression profiles (145 out of 17,448; Spearman = 105/17,448 = 0.60%), showing that this relationship is not statistically obligated." (PMID 32514083, 2020). "Dysfunction of prefrontal parvalbumin (PV+) interneurons has been linked with severe cognitive deficits as observed in several neurodevelopmental disorders including schizophrenia." (PMID 30792384, 2019). "Here, we utilized optogenetic and reverse-microdialysis approaches to modulate activity of the major subpopulation of TRN GABAergic neurons, which express the calcium-binding protein parvalbumin (PV), and are implicated in schizophrenia dysfunction." (PMID 30837664, 2019). "Postmortem studies of patients with schizophrenia showed a simultaneous decrease in the levels of parvalbumin interneurons (caused by changes in the expression of parvalbumin) and glutamic acid decarboxylase in the dorsolateral prefrontal cortex." (PMID 32116664, 2019). "Although more than 20 different classes of GABAergic interneurons exist, it has been suggested that in schizophrenia there is a loss of a particular type of GABAergic interneurons characterised by containing the calcium-binding protein parvalbumin (PV)." (PMID 31529297, 2019). "Dysfunction of parvalbumin (PV)-expressing interneurons is thought to underlie the alterations of gamma-band oscillations observed in schizophrenia." (PMID 29934499, 2018). "Loss of parvalbumin interneurons is one of the most robust findings from postmortem brains of schizophrenia patients." (PMID 27432008, 2016). "Loss of parvalbumin interneurons in the hippocampus and prefrontal cortex has been reported in many animal models of schizophrenia, including neonatal hippocampal lesion, maternal immune activation, amygdala disinhibition, and MAM-E17 models." (PMID 27432008, 2016). "Both preclinical genetic and environmentally based models using schizophrenia risk genes or stressors, respectively, have consistently observed a decreased number or impaired function of parvalbumin-positive interneurons in the hippocampus or cortex." (PMID 27725886, 2016). "Dysfunction of parvalbumin (PV)-positive GABAergic interneurons (PVIs) within the prefrontal cortex (PFC) has been implicated in schizophrenia pathology." (PMID 26608841, 2015). "Several studies on mutant mice of DISC1, one of the susceptible genes for schizophrenia, showed the reduction of parvalbumin-expressing interneurons in prefrontal cortices and CA region of hippocampus." (PMID 24528488, 2014). "Loss or dysfunction of parvalbumin-expressing interneurons has been linked to schizophrenia, Alzheimer’s disease, epilepsy and animal models of FASD (though it should be noted that loss of parvalbumin expression does not necessarily signal cell loss)." (PMID 24027632, 2013). "The cognitive deficits of schizophrenia appear to be associated with altered cortical GABA neurotransmission in the subsets of inhibitory neurons that express either parvalbumin (PV) or somatostatin (SST)." (PMID 22937123, 2012).
schizophrenia (continued). "This conclusion was indicated by a robust relationship between a FS cell maturation index and parvalbumin expression levels across multiple studies and a decrease in both measures in association with autism, schizophrenia, and bipolar disorder." (PMID 22936973, 2012). "This process and the consequent impairment of parvalbumin oligodendrocytes and interneurons may underlie alterations in brain connectivity in schizophrenia." (PMID 38732043, 2024). "For example, in schizophrenia, these regions contain lower levels of mRNA encoding parvalbumin and somatostatin, which are markers for respective interneuron subgroups that predominantly target either the cell body and initial axon segment, or dendritic shafts and spines of pyramidal neurons." (PMID 38363536, 2024). "A common hypothesis is that these alterations depend on a deficiency in GABAergic parvalbumin interneurons: these findings suggest a new model of cortical dysfunction in schizophrenia in which inhibition is decreased." (PMID 37007198, 2023). "With antioxidant and neuroprotector properties, taurine might be able to normalize the altered redox state and parvalbumin-positive interneuron loss found in animal models and patients with schizophrenia." (PMID 36239455, 2023). "Thirdly, in the mature brain, the GluN2D subunit is relatively enriched in parvalbumin (PV)-containing interneurons, a cell type hypothesized to underlie the cognitive symptoms of schizophrenia." (PMID 37511595, 2023). "Thus, we propose that the overactive DA system involved in schizophrenia psychosis is due to loss of parvalbumin inhibition of the ventral hippocampus and consequent overdrive of the DA system." (PMID 37569748, 2023). "Fast-spiking parvalbumin interneurons, which have been recurrently implicated in schizophrenia, contain high densities of mitochondria, are highly susceptible to oxidative stress, and may be particularly vulnerable to metabolic disruption." (PMID 35531971, 2022). "GABAergic interneurons, especially parvalbumin-positive neurons, have susceptibility to oxidative stress, thus the antioxidants had robust results in reversing the three symptom clusters in patients with schizophrenia." (PMID 33912003, 2021). "Parvalbumin-expressing interneuronal (In-PV) DEGs were also enriched for schizophrenia heritability, adding to the extensive evidence that In-PV are associated with schizophrenia." (PMID 34356078, 2021). "The pre-clinical methylazoxymethanol acetate (MAM) rodent model of psychosis shows reduced parvalbumin expression in MAM-treated rats that may be linked to schizophrenia-like pathology." (PMID 34146134, 2021). "Together, these data suggest that schizophrenia-related genetic variants are associated with cell types, particularly parvalbumin interneurons, and could explain functional disruptions across cortex." (PMID 32514083, 2020). "Finally, schizophrenia genetic risk is enriched among interneuron-linked genes and predicts cortical signal amplitude in parvalbumin-biased regions." (PMID 32514083, 2020). "PVALB is a calcium-binding albumin protein that is expressed particularly by the fast-spiking class of GABAergic (gamma-aminobutyric acidergic) interneurons that has been strongly implicated in the pathogenesis of schizophrenia." (PMID 32029217, 2020). "There is increasing evidence that redox dysregulation, which can lead to oxidative stress and eventually to impairment of oligodendrocytes and parvalbumin interneurons, may underlie brain connectivity alterations in schizophrenia." (PMID 31283822, 2019). "Parvalbumin interneurons are fast-spiking GABAergic neurons that provide inhibitory control of cortical and subcortical circuits and are thought to be a key locus of the pathophysiology underlying schizophrenia." (PMID 31529297, 2019).
schizophrenia (continued). "Stress-induced hyperreactivity of the amygdala leads to the loss of parvalbumin interneurons and changes in their proportions in the hippocampus, which leads to even greater hyperexcitation of dopamine systems, and this causes symptoms of schizophrenia." (PMID 32116664, 2019). "Consistent findings of dendritic spine loss on pyramidal cells in areas like the DLPFC and dysfunction within glutamatergic channels (e.g., NMDA, AMPA) could contribute to this loss of excitatory input onto parvalbumin+ basket cells in schizophrenia." (PMID 30425662, 2018). "Interestingly,susceptibility of the parvalbumin population has been reported inneuropsychiatric diseases like schizophrenia, epilepsy and ASD2,44." (PMID 29086765, 2018). "Loss of parvalbumin interneurons in the hippocampus is a robust finding in schizophrenia brains." (PMID 27432008, 2016). "Reduced function of parvalbumin (PV) interneurons and disruption of GABAergic synapses in the cortical circuitry result in desynchronized network activity associated with cognitive impairment across many psychiatric disorders, including schizophrenia." (PMID 27163207, 2016). "Moreover, studies in the prenatal methylazoxymethanol acetate (MAM) rat model of schizophrenia, which shows a loss of parvalbumin GABA interneurons and hyperactivity in the VH, also reported the absence of LI, which was mediated by reduced conditioning in the NPE group." (PMID 34980662, 2022). "In addition, postnatal ablation of mGlu5 receptors from parvalbumin (PV)-positive interneurons caused a schizophrenia-like phenotype in adult mice, characterized by impaired rhythmic cortical oscillatory activity and alterations in sensory-motor gating, learning and memory, and social recognition." (PMID 33962661, 2021). "Parvalbumin interneurons are fast-spiking neurons that are critical to the generation of gamma oscillations, a type of high-frequency neuronal oscillation linked to working memory and other cognitive processes in healthy subjects and patients with schizophrenia." (PMID 31529297, 2019). "While the previous consistent findings indicate that hypermethylation of PVALB at CpG2 might be generally associated with psychotic illness and animal model of schizophrenia, these results suggest that this epigenetic change may extend to other psychiatric disorders, in this case MDD." (PMID 31588185, 2019). "Thus, a reduced dendritic spine density on pyramidal neurons and a loss of parvalbumin–immunoreactive interneurons in the cerebral cortex may be core features of histological changes in the brain of schizophrenia patients." (PMID 29515467, 2018). "MAM-E17 exposed rats model a wide range of neuroanatomical abnormalities associated with schizophrenia, including reduced frontal cortical thickness, increased ventricle volume, and a loss of prefrontal cortical and ventral hippocampal parvalbumin-expressing (PV+) interneurons." (PMID 23141065, 2012). "Chemogenetic activation of parvalbumin interneurons alleviates cognitive deficits in schizophrenia mouse models." (PMID 40931040, 2026). "Specifically, we found higher levels of the presynaptic marker for Parvalbumin interneurons synaptotagmin II (Syt2), mirroring observations made in the brain of schizophrenia patients." (PMID 42185248, 2026). "We selected immunohistochemistry and mRNA studies that examined parvalbumin, somatostatin, calbindin, and calretinin interneuron density or expression in schizophrenia patients." (PMID 40501558, 2025). "These postmortem studies have consistently revealed reduced expression of GABA-related markers, such as the enzyme glutamic acid decarboxylase (GAD67) and parvalbumin (PV), in the prefrontal cortex of individuals with schizophrenia." (PMID 40358174, 2025). "Excitatory synapses on parvalbumin expressing interneurons contain similar AMPA but significantly lower NMDA receptor densities in schizophrenia compared with control subjects." (PMID 40829937, 2025).